IL6 (interleukin 6)
Diseases named in the same sentence as IL6 in open-access papers (continued):
Sharing a sentence is not in itself a finding about the gene and the disease.
lung carcinoma (continued). "In a previous study, we established a model of cancer-related anemia in mice by the subcutaneous inoculation of cells of the IL-6–producing human lung cancer cell line LC-06-JCK." (PMID 27068103, 2016). "Because IL-6 is involved in the pathophysiology of various solid tumors, such as lung cancer, the clinical use of this antibody has been analyzed in different contexts." (PMID 27445423, 2016). "In lung cancer, it has been reported that patients with IL-6 overexpression have a poor response to chemotherapy, which is important because IL-6 is administered in combination with cancer treatments because of its ability to induce platelet production." (PMID 27445423, 2016). "Interleukin-6 (IL-6) is a pro-carcinogenic inflammatory cytokine that plays a pivotal role in lung cancer development." (PMID 26372664, 2016). "Our previous studies demonstrate that ATM phosphorylation and elevated IL-6 level contribute to chemotherapeutic agents-inducing MDR formation in lung cancer." (PMID 26528698, 2015). "As MMP-3/MMP-13 plays the pivotal roles in TNF-α increased metastasis, we therefore investigated the role of MMP-3/MMP-13 in IL-6 enhanced lung cancer metastasis." (PMID 26528698, 2015). "Previous reports have shown that IL-6 can be expressed in lung cancer cell lines and the lungs of patients after radiotherapy." (PMID 26425690, 2015). "In conclusion, our data indicate that aberrant Akt signalling contributes to maintaining stemness in lung cancer TICs through a NF-kB/IL-6/STAT3 pathway and provide novel potential therapeutic targets for eliminating these malignant cells in NSCLC." (PMID 26486080, 2015). "IL-6 levels are elevated in lung cancer patients in cells lines with endothelial growth factor receptor (EGFR) mutations which results in STAT3 elevation." (PMID 26220864, 2015). "EGFR and KRAS mutations, activation of Src kinase, and elevated expression of interleukin-6 (IL-6) are among several molecular aberrations have been identified in lung cancer that often result in the activation of STAT3." (PMID 26314961, 2015). "Studies of the IL-6 mechanism of action suggests that IL-6 promotes lung cancer cell proliferation and migration through activation of the transcription factor Signal Transducer and activator of Transcription 3 (STAT3)." (PMID 26517240, 2015). "In the present study, our results reveal that IL-6 inducing ATM phosphorylation increases lung cancer metastasis via up-regulation of MMP-3/MMP-13." (PMID 26528698, 2015). "Three prominent cytokines produced in the COPD are TNF-α, IL-1, and IL-6, and these all also have important roles in lung cancer." (PMID 26220864, 2015). "IL-6 is a pleotropic proinflammatory cytokine that has been shown to be expressed in over 50% of NSCLC and is associated with poor survival of lung cancer patients." (PMID 26517240, 2015). "The findings reported here extend previous observations that IL-6 is overexpressed in lung cancer and point to activation of PI3K/Akt pathway as one of the causes of the observed IL-6 overproduction." (PMID 26486080, 2015). "For instance, recent data reveal that DNA methylation is frequent in promoter regions of IL-1b, IL-6 and IL-8 in lung cancer." (PMID 25590298, 2015). "The results described here in human, complement also data from murine models of lung cancer, which have shown that IL-6/STAT3 signaling facilitates cancer progression by promoting cell growth." (PMID 26486080, 2015). "Together, these data demonstrate that MMP-3 and MMP-13 are the key MMPs in IL-6 promoting lung cancer metastasis." (PMID 26528698, 2015). "Previous studies have demonstrated that higher levels of IL-6 existed in advanced and metastatic cancer patients in their blood including the lung cancer patients." (PMID 26166037, 2015). "Most importantly, the in vivo test showed that the inhibition of ATM abrogate the effect of IL-6 on lung cancer metastasis via MMP-3/MMP-13 down-regulation." (PMID 26528698, 2015).
lung carcinoma (continued). "Recently, this autocrine mechanism was demonstrated in human lung cancer cells secreting IL-22- and IL-6- induced STAT3 phosphorylation, thus contributing to the pathogenesis of lung adenocarcinoma and formation of pleural effusion." (PMID 25793261, 2015). "But until now, little is known about the roles of MMP-3 and MMP-13 in IL-6 correlated lung cancer metastasis." (PMID 26528698, 2015). "To explore the effect of IL-6 on cell migration, we firstly determined IL-6 levels in a panel of lung cancer cells." (PMID 26528698, 2015). "HGF and IL-6 have been shown to cooperatively enhance lung cancer cell invasion by upregulation of their corresponding cell surface receptors." (PMID 26268945, 2015). "All these results indicate that IL-6 increases MMPs expressions and activities in lung cancer cells." (PMID 26528698, 2015). "In patients with lung cancer, polymorphisms in TNF and IL6 were significantly associated with pain severity (for TNF, GG = 4.12; GA = 5.38; AA = 5.50; p = 0.04) and with morphine-equivalent daily dose (IL-6, GG = 69.61; GC = 93.6; CC = 181.67; p = 0.004)." (PMID 26269716, 2015). "MSC conditioned medium favored lung cancer cell proliferation and lung cancer cells stimulated the expression of IL-6, IGF-1, VEGF and DKK1 on MSCs." (PMID 26582222, 2015). "As a previous study indicated that JAK1 is the critical JAK kinase contributing to STAT3 activation and mediates IL-6-induced STAT3 activation in lung cancer cells, we next determined the effect of NOX4 overexpression on JAK1/STAT3 activity in A549 cells." (PMID 25504436, 2015). "Apart from transforming growth factor beta (TGF-β), IL-6 has been documented to be involved in lung cancer EMT via signal transducer and activator of transcription 3 (STAT3), Notch pathway." (PMID 26528698, 2015). "We found that brassinin (BSN) suppressed both constitutive and IL-6-inducible STAT3 activation in lung cancer cells." (PMID 25788267, 2015). "Compounds 1–4 were all found to inhibit the expression of proinflammatory cytokines IL-6 or MCP-1 induced by influenza H1N1 virus in human A549 lung carcinoma cells." (PMID 24727419, 2014). "In patients with chemotherapy-resistant lung cancer, a high IL-6 serum level correlated strongly with survival, and the cut-off level for affecting their prognosis was 21 pg/mL." (PMID 25010770, 2014). "Overproduction or dysregulation of IL-6 by macrophages can contribute to the growth and metastasis of many carcinomas, including lung cancer." (PMID 26316944, 2014). "In that context, we previously reported that tocilizumab had remarkably ameliorated a patient’s cancer cachexia induced by an IL-6 over-expressing lung cancer." (PMID 25010770, 2014). "Even with IFN-γ and LPS stimulation, IL-6 inhibited the development of tumoricidal function in AMs of patients with lung cancer." (PMID 26316944, 2014). "To elucidate the role of IL-6 in cachexia induced by lung cancer, we previously established a lung cancer cell line transfected with IL-6 cDNA and transplanted these cells into C57BL/6 mice." (PMID 25010770, 2014). "A number of pro- and/or anti-inflammatory cytokines have been described as possessing dual roles in lung cancer including TNFα, IL-6, IL-8, IL-10, VEGF, and PDGF." (PMID 26316944, 2014). "What is more, a significant correlation of TP with IL-1β (R = 0.514, p = 0.001) and IL-6 (R = 0.519, p = 0.002) was observed thus confirming our data from the animal model showing a potential novel effect of TP upregulation in the carcinoma of the lung." (PMID 24819505, 2014). "Elevated IL-6 levels contribute to malignant pleural effusion, postoperative complications, and postoperative recurrence of lung cancer." (PMID 24260500, 2013). "Interleukin-6 (IL-6) is involved in lung cancer tumorigenesis, tumor progression, metastasis, and drug resistance." (PMID 24260500, 2013). "Consequently, this may pose a risk to lung cancer patients treated with IL-6-targeted therapy." (PMID 24260500, 2013).
lung carcinoma (continued). "We further demonstrated that genetic ablation of IL-6 results in significant tumor suppression in this model in vivo, indicating an essential role for IL-6 in lung cancer promotion in this model." (PMID 24321240, 2013). "In our study, we showed that surface TF expression was regulated by IL-6/Stat3 signaling, and TF-induced coagulation was decreased by inhibiting Stat3 activation in lung cancer cells." (PMID 24086497, 2013). "Several studies have correlated high circulating IL-6 levels with poor survival of lung cancer patients." (PMID 24260500, 2013). "IL-6 expression can be detected in lung tumors and in 53% of lung cancer cell lines, and IL-6 pathways are activated in a human lung cancer stem cell line." (PMID 24260500, 2013). "An IL-6 monoclonal antibody therapy would be predicted to inhibit the inflammatory microenvironment in lung cancer." (PMID 24260500, 2013). "Taken together, our data clearly demonstrate that autocrine IL-6-induced Stat3 activation regulates membrane TF expression in lung cancer cells." (PMID 24086497, 2013). "Taken together, these results indicate that IL-6 deletion accelerates tumorigenesis but delays tumor progression and prolongs survival time in a Kras-driven mouse model of lung cancer." (PMID 24260500, 2013). "This prophylactic effect of rhubarb on lung cancer patients treated with radiotherapy has been explained by decreasing the level of transforming growth factor-beta-1 and interleukin-6." (PMID 24280678, 2012). "CDA-2 and PG significantly reduced NF-κB DNA-binding activity in lung cancer cells and in alveolar macrophages of tumor bearing mice and especially decreased the release of inflammatory factors including TNFα, IL-6, and KC." (PMID 23284890, 2012). "To explore the heterogeneity among studies of IL-6 and lung cancer, we performed sensitivity analyses." (PMID 22912790, 2012). "The 5 studies on IL-6 (3 cohort, 1 nested case-control, and 1 case-control study) were published between 2005 and 2011 and involved a total of 924 lung cancer cases." (PMID 22912790, 2012). "The pooled RR of lung cancer for one unit change in ln IL-6 was 1.28 (95% CI 0.92–1.79), however, statistically significant heterogeneity was found." (PMID 22912790, 2012). "The observation of reduction in estrogen in lung cancer patient's serum is a novel finding and was supported by the high rate of CYP1A1 genetic polymorphism and increased expression of IL-6 in serum." (PMID 26316937, 2012). "We have previously shown an essential role for IL-6 in promotion of lung cancer by airway inflammation." (PMID 22239913, 2012). "Some types of tumors produce IL-6, for example, elevation of serum IL-6 levels is found in up to 60% of lung cancer patients in advanced stages." (PMID 21951917, 2011). "The JAK/STAT signaling axis is a key modulator of cytokine signaling and one proposed mechanism for aberrant STAT3 activation in lung cancer involves the upregulation of autocrine and/or paracrine IL-6 signaling." (PMID 21533169, 2011). "To do this, we pharmacologically inhibited the four IL-6 downstream pathways in 20 clinical samples of human lung cancer obtained from MPE." (PMID 21122157, 2010). "In the present study, we took cancer cells from MPE of lung cancer patients and found that IL-6 regulation in human lung cancer samples to be similar to that in cancer cell lines." (PMID 21122157, 2010). "We recently showed that a principal mechanism of Stat3 activation in breast and lung cancers is through autocrine production of IL-6." (PMID 20929542, 2010).
lung carcinoma (continued). "Serralysin of Serratia marcescens is a protease that induces IL-6 and IL-8 expression in lung carcinoma cells." (PMID 19293938, 2009). "IL-6 promotes lung cancer growth and metastasis and we have demonstrated that IL-12 dampens IL-6 production in mouse splenocytes." (PMID 19582164, 2009). "We sought to identify cellular changes in IL-6 cytokine signaling that correlate with attenuated growth suppression of lung cancer cells." (PMID 16271139, 2005). "A more common observation in lung cancer is the enhanced signaling by IL-6 cytokine receptors towards the STAT and ERK pathway." (PMID 16271139, 2005). "Serum interleukin 6 (IL-6) levels were measured in 75 patients with lung cancer and in 20 patients with benign lung diseases." (PMID 7734307, 1995). "We found that lung cancer cell lines secreted a large amount of IL-6 under hypoxic conditions." (PMID 41254082, 2025). "Pro-inflammatory cytokines relevant to pulmonary oncology intersect with checkpoint pathways: IL-6 trans-activates JAK/STAT3 in lung cancer and can upregulate PD-L1, while EGFR signaling on tumor cells converges on the IL-6–STAT3 axis to enhance PD-L1 expression." (PMID 41440526, 2025). "Some of the inflammatory factors involved in lung cancer are IL-6, IL-11, IL-12 and TNF-α." (PMID 40407951, 2025). "Potential upstream activators of STAT3 in lung cancer include IL-6, which has been reported to be constitutively produced in some lung cancer cell lines and lung cancer patients, and EGFR, which is often overexpressed or mutated in the kinase domain in NSCLC cells." (PMID 41380973, 2025). "IL-6 was essential for MAPK activation; even with oncogenic KRAS mutations, the absence of IL-6 halted cancer development in PDAC mouse models and was shown to prevent initiation while enhancing the progression of lung cancer driven by KRAS mutations." (PMID 40611261, 2025). "Additionally, NINJ1 inhibits the IL-6 signaling pathway both in vitro and in vivo, suppressing lung cancer migration, invasion, and metastasis." (PMID 39980566, 2025). "Interestingly, patients with lung cancer have been shown to have the highest IL-6 levels, which positively correlate to its role in cancer progression and therapeutic resistance during tumor development." (PMID 41376623, 2025). "In this comprehensive article, we lay down insights on the gut-lung axis, a detailed perspective on the existing correlation between gut microbiome and lung cancer, with a special focus on the role of pleiotropic cytokines, IL-6 and IL-17, in regulating this axis in NSCLC development." (PMID 41376623, 2025). "Circulating levels of IL-6 and IL-8 may predict response to immunotherapy in lung cancer patients, potentially through their influence on neutrophil activity." (PMID 41254689, 2025). "However, according to other reports, the IL-6 concentration was lower at baseline or before lung cancer progression than during disease progression in patients treated with osimertinib." (PMID 40156608, 2025). "Additionally, a limited number of advanced lung cancer patients treated with neutralizing antibodies against IL‐6 or its receptor (IL‐6R) experienced amelioration of cachexia‐related symptoms." (PMID 39764565, 2025). "Our findings suggest that targeting IL-6 may be a worthwhile therapeutic strategy in the management of lung cancer in smokers." (PMID 38993553, 2024). "In vitro, TLR8 agonist stimulation of lung cancer cells resulted in the activation of NF‐κB, increased expression of proinflammatory factors (IL‐6, IL‐8, GM‐CSF, IL‐1α, and IL‐12), and increased expression of antiapoptotic proteins Bcl‐2, VEGFR2, and chemokine receptors." (PMID 39003635, 2024). "Finally, IL-6 controls bone resorption activity and regulates lung cancer-related osteolytic bone metastasis." (PMID 38993553, 2024). "A novel mechanism of macrophage-promoted tumor progression was revealed, and the IL6-STAT3-C/EBPβ-IL6 signaling cascade may be a potential therapeutic target against lung cancer." (PMID 38424624, 2024).
lung carcinoma (continued). "In lung cancer, IL-6 has an expanding role in inducing the expression of cell cycle proteins." (PMID 38279220, 2024). "IL-6 and the NFkB signaling axis connect chronic inflammation to lung cancer." (PMID 38279220, 2024). "Notably, IL-6 has also been reported as a prognostic predictor of ICI therapy in lung cancer and melanoma." (PMID 38580797, 2024). "Importantly, blocking IL-6 abolished cigarette smoke-facilitated lung cancer osteolytic bone metastasis in vivo." (PMID 38993553, 2024). "Additionally, TNF-α, IL-6, and IL-1β induce elevated Ido1 expression in the context of immunosuppression in lung cancer progression." (PMID 39759510, 2024). "This gene has also been proposed as a potential biomarker for lung cancer after finding that it interacts with STAT3 in lung cancer cells, regulating IL-6 and thus mediating inflammatory processes, while another study determined that its blockade inhibited lung cancer cell growth." (PMID 39361370, 2024). "Additionally, aberrantly high levels of serum IL-6 are detected in patients with lung cancer compared to those in benign pulmonary lesions." (PMID 38529301, 2024). "The presence of adiponectin and IL-6 in the bone marrow microenvironment of lung cancer bone metastasis suggests that BMAs may promote EC growth and new blood vessel formation, providing additional nutrients and pathways for cancer metastasis." (PMID 38571500, 2024). "IL-6 secreted by TAMs acts on lung cancer to promote their metastasis through activation of EMT." (PMID 38424624, 2024). "Furthermore, interleukin-6 (IL-6) has been shown to promote lung cancer growth by inducing inflammatory responses." (PMID 38371298, 2024). "The IL-6 cytokine is associated with epithelial–mesenchymal transition, lung cancer development, progression, and the tumor metastasis of non-small cell lung cancer." (PMID 39599846, 2024). "In the current investigation, compared to a lung cancer control, chia seed oil and hydroethanolic extract significantly decreased the expression of IL-6 and IL-1β (by around 10.8 and 13.17% for ether extract and 4.25 and 11.20% for alcohol extract, respectively)." (PMID 39338293, 2024). "Studies in lung cancers highlighted that IL6 protects cancer stem cells (CSCs)." (PMID 39766086, 2024). "A few biological pollutants have been reported to promote lung cancer via inducing inflammatory cytokines secretion, such as IL-1β, IL-6, and TGF-β, as well as suppressing immunosurveillance by upregulating regulatory T (Treg) cells while dampening the function of CD8+ T cells and dendritic cells." (PMID 38542056, 2024). "Furthermore, IL-6 is considered a reliable prognostic factor for lung cancer patients, as it is correlated with patients' progression, therapy resistance, poor survival, and postoperative complications." (PMID 38103126, 2024). "IL-6 significantly increases invasion in lung cancer cells by regulating EMT." (PMID 38836056, 2024). "Interestingly, IL-6 has been greatly upregulated in lung cancer, and a molecular link has been suggested via the transcription factor signal transducer and activator of transcription 3 (STAT3) pathway." (PMID 38103126, 2024). "Moreover, ERK5 can enhance the production of interleukin-6 (IL-6), aiding lung cancer cells in evading anti-tumor immune responses, and can also amplify the DNA damage response, increasing lung cancer cells’ resistance to radiotherapy." (PMID 38785963, 2024). "Additionally, it has been clearly shown that IL-6 plays an essential role in lung cancer promotion, and its blockade significantly inhibits lung cancer development, STAT3 activation in tumor cells, tumor cell proliferation, and angiogenesis markers." (PMID 37894302, 2023). "Serum levels of IL-6, IL-1β, and IFN-γ were associated with lung cancer risk." (PMID 38067398, 2023).